BCL2 (BCL2 apoptosis regulator)
Diseases named in the same sentence as BCL2 in open-access papers (continued):
Sharing a sentence is not in itself a finding about the gene and the disease.
gastric cancer (continued). "To further investigate the molecular mechanisms involved in ATF4-related MDR of gastric cancer, we also examined MDR1, MRP, Bcl-2, and Bax expression levels in the gastric cancer cells used above." (PMID 22363646, 2012). "Our results showed that Tob1 induced Bax expression and inhibited Bcl-2 expression in gastric cancer cells." (PMID 22710759, 2012). "Caspase-3, caspase-8, and Bax protein levels increased after 48 h of treatment with SF-CM from most gastric cancer cells, while bcl-2 protein levels decreased." (PMID 22520554, 2012). "Treatment with the HDAC inhibitor sodium butyrate increased the expression of caspase-3 and DAPK1/2 genes but decreased the expression of Bcl-2 in human gastric cancer cells." (PMID 22160140, 2012). "As there is a significant possibility that gastric cancer cell-mediated apoptosis of mesothelial cells is the result of regulation of Bcl-2 and Bax, identification of their target compounds is necessary." (PMID 22520554, 2012). "It has been well defined that Bcl-2 can be targeted and regulated by microRNAs such as miR-15b and miR-16 in gastric cancer cells." (PMID 22920753, 2012). "In our study, we found that nasopharyngeal, breast and gastric cancer cell lines resistant to gemcitabine had higher Bcl-2 expression, and treatment with gemcitabine resulted in an up-regulation of anti-apoptotic Bcl-2 or Bcl-xl." (PMID 23226540, 2012). "In conclusion, the expression of bcl-2 can serve as one useful indicator for predicting the prognosis of patients with gastric cancer." (PMID 22216342, 2011). "It has been reported that the over expression of Runx3 in gastric cancer cells down regulates Bcl-2 and directly activates the promoter activity of Bim to enhance TGF-β-dependent apoptosis, therefore, sensitizes cancer cells to chemotherapeutic drugs." (PMID 24250365, 2011). "In present study, we characterized for the first time the expression of bcl-2 proteins in Chinese gastric cancer patients." (PMID 22216342, 2011). "For example, miR15b and miR-16 were demonstrated to play a role in the development of MDR in gastric cancer cells by targeting the antiapoptotic gene BCL2." (PMID 22216150, 2011). "bcl-2 has been reported in a variety of human epithelial malignant tumors including gastric carcinoma." (PMID 22216342, 2011). "It is considered that the high levels of Bcl-2 expression adopted as protection from apoptosis in EBV-positive gastric cancer cells result in the natural death of fewer cancer cells than in the case of EBV-negative gastric cancer cells." (PMID 20704765, 2010). "The present study suggests that Hh signaling regulates the survival of gastric cancer cells by regulating the expression of Bcl-2." (PMID 19742123, 2009). "In the present study, we show that Bcl-2 is involved in cyclopamine-induced apoptosis in gastric cancer cells." (PMID 19742123, 2009). "In the present study, we show that Hh signaling regulates the survival of gastric cancer cells by regulating the expression of Bcl-2." (PMID 19742123, 2009). "The present study shows that Hh signaling regulates the survival of gastric cancer cells by regulating the expression of Bcl-2." (PMID 19742123, 2009). "Our data demonstrate that miR-34 restoration can chemosensitize those gastric cancer cells that have high levels of Bcl-2 and low basal levels of miR-34, which are dependent on Bcl-2 for survival and drug resistance." (PMID 18803879, 2008). "Human gastric cancer Kato III cells with miR-34 restoration reduced the expression of target genes Bcl-2, Notch, and HMGA2." (PMID 18803879, 2008).
gastric cancer (continued). "This study was designed to immunohistochemically evaluate the CD117 and bcl-2 expression in gastric carcinomas and their potential use as therapeutic targets in the treatment of patients with advanced stage gastric cancer." (PMID 16759362, 2006). "Chen and colleagues reported 80.56% of immunohistochemical reactivity of gastric cancer cells to bcl-2 protein which was irrespective to tumor location, histologic type of cancer, and lymph node metastasis status." (PMID 16759362, 2006). "But further large studies needed to perform in order to verify the exact rate of bcl-2 reactivity in gastric carcinoma." (PMID 16759362, 2006). "The expression of bcl-2 in gastric carcinoma seems to be quite rare and currently its clinical significance is unclear." (PMID 16759362, 2006). "Based on the literature, the overexpression of miR-15b may contribute to the development of multidrug resistance in gastric cancer cells, potentially by targeting the apoptotic protein BCL-2, a key regulator of apoptosis." (PMID 41462911, 2025). "ATL-2 from AMK • Inhibited proliferation and induced apoptosis• Reduced cell motility• Downregulated p-Akt and p-ERK• Increased Bax/Bcl-2 ratio• ATL-2 exerted significant anti-tumor effects on the gastric carcinoma cells by modulating Akt/ERK signaling pathway." (PMID 40144663, 2025). "Moreover, some agents also impact the expression of transcription factors and proteins related to EMT and apoptosis, such as Snail, E-cadherin, Bax, and Bcl-2, further impeding gastric cancer progression." (PMID 39906672, 2024). "Instead, curcumin downregulates Bcl-2 expression through the induction of miR-15a and miR-16 in breast cancer, it enhances the expression of miR-34a in gastric cancer, and it inhibits the expression of miR-21 directly associated with tumor cell invasion and metastasis in human colon cancer cells." (PMID 39858410, 2024). "The genes targeted by AMK in the context of gastric cancer include apoptosis regulator Bcl-2 (BCL2), catenin beta 1 (CTNNB1), B-cell stimulatory factor 2 (IL6), mutated in multiple advanced cancers 1 (PTEN), proto-oncogene (SRC), and tumor necrosis factor ligand member 2 (TNF)." (PMID 38612999, 2024). "It is known that BCL2 expression level is increased as gastric cancer progresses." (PMID 38612999, 2024). "Moreover, an in vitro study showed that it exerted anticancer effect against SGC-7901 human stomach cancer cells by inducing apoptosis by decreasing the bcl-2/bax ratio and eliciting DNA damage." (PMID 39478959, 2024). "“In vivo” studies also demonstrated that EGCG could modulate miRNAs in cancers such as hepatocellular carcinoma and gastric cancer, targeting critical genes like c-Kit, Bcl2, E2F, and RAS." (PMID 39858410, 2024). "It has been reported that overexpression of microRNA-181b (miR-181b) and microRNA-497 (miR-497) can induce apoptosis and reverse drug resistance through decreasing the expression of Bcl-2 in vincristine-resistant gastric cancer and cisplatin-resistant lung cancer." (PMID 38542707, 2024). "BCL2 inhibits the mitochondrial pathway of apoptosis and plays an important role in the progression of gastric cancer, which is closely related to the severity of gastric cancer." (PMID 38612999, 2024). "In cisplatin-resistant gastric cancer, production of miR-21 by TAMs was shown which decreased PTEN activation, and enhanced activation of the PI3K/AKT pathway and production of Bcl-2, therefore, decreasing apoptosis rate and cisplatin sensitivity of gastric cancer cells." (PMID 38794298, 2024). "Similarly, gallic acid was able to induce apoptosis through Fas, FasL and DR5 expression upregulation; caspase-8, -9 and -3 activation; bad and bak protein expression increase; and bcl-2 decrease in AGS gastric cancer cells." (PMID 36675194, 2023). "In addition, CM-DOP promoted the apoptosis of gastric cancer cells by upregulating Caspase-3 and increasing the ratio of Bax/Bcl-2." (PMID 37894541, 2023).
gastric cancer (continued). "In addition, we also detected expression levels of multiple apoptotic proteins (BAX, BAK and BCL-2) in gastric cancer xenografts, which indicated the pro-apoptotic of LINC00240." (PMID 37072811, 2023). "Specifically, these compounds promote apoptotic bleb formation, as they affect the expression of pro-apoptotic and anti-apoptotic proteins such as Bad, Bax, Mcl-1, and Bcl-2, leading to a delicate balance shift tipping the scales towards apoptosis in gastric cancer cells." (PMID 37958986, 2023). "In addition, regarding the pro-apoptotic effect of quercetin, it has been shown that this flavonoid acts through the induction of the expression of Bax and caspase-3 proteins and, in contrast, by reducing the level of Bcl2 in BGC-823 gastric carcinoma cells." (PMID 36673507, 2023). "Interestingly, the levels of cells with inactivated Bcl-2 were higher in colon HT-29 cancer cells than in AGS gastric cancer cells across different conditions." (PMID 36296971, 2022). "Although it is required to unravel the mechanisms underlying the oncogenic role of CEBPA-AS1 in gastric cancer, apoptosis may nonetheless be regulated by the CEBPA-AS1/BCL2 axis in gastric cancer as well." (PMID 35055115, 2022). "However, ApoG2 reduced colony formation to a greater extent than gossypol and inhibited gastric cancer cell growth and proliferation by downregulating Bcl-2, upregulating Bax, and activating caspase-3." (PMID 36559116, 2022). "Its effect on gastric cancer apoptosis was revealed through Bax, BCL-2, and caspase analyses." (PMID 35586683, 2022). "Moreover, in the gastric cancer line, KLF10 overexpression altered the Bcl-2/Bax ratio, caused caspase-3 activation, and finally, caused apoptosis." (PMID 35743973, 2022). "GSE1 positively regulated the expression of BCL-2, and the promoting role of GSE1 in trastuzumab resistance of HER2 positive gastric cancer might consequently be mediated by BCL-2." (PMID 33623790, 2021). "The promoting role of GSE1 in trastuzumab resistance of gastric cancer cells might be mediated by BCL-2." (PMID 33623790, 2021). "Notably, PVT1 enhanced Bcl2 expression in gastric cancer cells, thereby inhibiting apoptosis and promoting resistance to 5-fluorouracil." (PMID 34564701, 2021). "Radix, increased the sub G1 population of the cell cycle and decreased p65, bcl-2, Fas, and smac mRNA expression, and increased IκBα, bax, and survivin mRNA expression, which induced apoptosis of the human gastric cancer cell line BGC823 through down-regulation of the NF-κB pathway." (PMID 34572730, 2021). "Moreover, knockdown of gastrin is associated with deactivation of NF-κB in a ROS-dependent manner in gastric cancer cells and upregulation of Bax and downregulation of Bcl-2, thus promoting apoptosis." (PMID 33937399, 2021). "We doubted whether BCL-2 also mediated the promoting role of GSE1 in gastric cancer stem cell behaviors." (PMID 33623790, 2021). "The trastuzumab-resistance promoting role of GSE1 might be mediated by BCL-2 in HER2-positive gastric cancer cells." (PMID 33623790, 2021). "Also, TIPE2 is reported to elicit cell apoptosis by activating caspase three and caspase 9, inducing the cleavage of PARP, and inhibiting bcl-2 expression in BGC-823 gastric cancer cells." (PMID 34630074, 2021). "Therefore, BCL-2 was positively regulated by GSE1, and BCL-2 also promoted trastuzumab resistance of gastric cancer cells." (PMID 33623790, 2021). "Therefore, we herein proved that BCL-2 was also a promoter of trastuzumab resistance in HER2-positive gastric cancer cells." (PMID 33623790, 2021). "BCL-2 was also reported to promote multidrug resistance in gastric cancer cells." (PMID 33623790, 2021). "Moreover, a combination of rutin and chemotherapeutic agent Oxaliplatin promoted apoptosis of gastric cancer cells SGC-7901 demonstrated through decreased BCL-2/Bax ratio while the apoptotic mechanisms of rutin were related to caspase-mediated signaling." (PMID 34439088, 2021).
gastric cancer (continued). "Using Human apoptosis antibody array, we found that NDUFC1 knockdown may promote gastric cancer cell apoptosis through downregulating Bcl-2, clAP-2, Survivin, sTNF-R1, and XIAP." (PMID 34966665, 2021). "Several previous reports revealed that TIPE2 could inhibit the expression of bcl2 and suppress mitochondrial apoptosis as a tumor suppressor in gastric cancer cells and other tumor cells." (PMID 34630074, 2021). "The results of qRT-PCR confirmed that 25 μM evodiamine could upregulate the expression of proapoptotic Bax and downregulate the antiapoptotic Bcl-2 in gastric cancer cells, resulting in the upregulation of Bax/Bcl-2 ratio." (PMID 34824590, 2021). "Our findings showed that HDAC inhibitors E2F5 and BCL2 are the therapeutic candidates for gastric carcinomas, which agrees with the hypothesis of HDAC being overexpressed in gastric cancer cell lines." (PMID 34947956, 2021). "Similarly in gastric cancer cells, KD of Rab31 by siRNA reduced expression of the BCL-2, Hedgehog (Hh) signaling transcript GLI1 while increasing BAX protein levels." (PMID 31973201, 2020). "Furthermore, the qRT-PCR and western blotting assays showed that the transcriptional and protein levels of MCL1 and BCL2 in BCL2-drug-resistant gastric cancer cell lines were higher than those in normal gastric cancer cell lines." (PMID 33126914, 2020). "Similarly, Bcl-2 silencing by miR-429 has also been found to sensitize gastric cancer cells to 5-FU." (PMID 32192494, 2020). "Moreover, PDX (Patient-Derived tumor xenograft) model experiment proved that LH combined with HA14–1 (inhibitor of BCL2), had a more significant therapeutic effect on gastric cancer." (PMID 33126914, 2020). "Moreover, lycopene induced apoptosis through increased DNA fragmentation, caspase-3, and caspase-9 cleavage, and BAX/Bcl-2 ratio increase in AGS gastric cancer cells." (PMID 32859058, 2020). "Exogenous expression of miR-135a-5p could enhance apoptosis resistance to ADR in gastric cancer cells via silencing activating protein 2 alpha (AP-2α) and, thus, upregulating Bcl-2 expression." (PMID 32192494, 2020). "Moreover, fucoxanthin inhibited viability, induced autophagy and apoptosis through upregulation of beclin-1, microtubule-associated proteins 1A/1B light chain 3 (LC3), and cleaved caspase-3, and downregulation of Bcl-2 in SGC7901 gastric cancer cells." (PMID 32859058, 2020). "Therefore, the sensitivity of gastric cancer cell lines to APG‐1252‐M1 was related to the basic level of Bcl‐2, Bcl‐xl, and Bax." (PMID 32346976, 2020). "Subsequently, western blotting showed that LH could also induce the up-regulation of apoptosis-related proteins, C-Caspase 9, C-Caspase 3 and C-PARP in BCL2-drug-resistant gastric cancer cell lines with a dose and time gradient effect." (PMID 33126914, 2020). "In addition, miR-202-3p inhibited gastric cancer activity by inhibiting the expression of catenin and BCL-2." (PMID 33520978, 2020). "Tumor suppressors miR-15b, miR-16, miR-181b and miR-497 could promote ADR-induced apoptosis of gastric cancer cells via silencing Bcl-2 expression." (PMID 32192494, 2020). "It has been found that by targeting and suppressing Bcl-2 expression, tumor suppressor miR-15b, miR-16, miR-181b, miR-497 and the miR-200bc/429 cluster could sensitize gastric cancer cells to etoposide or mitomycin." (PMID 32192494, 2020). "By inhibiting the Bcl-2 signaling pathway, several tumor suppressor miRNAs, including miR-15b, miR-16, miR-181b, miR-497, the miR-200bc/429 cluster, miR-34 as well as miR-449a, have been found to sensitize gastric cancer cells to DDP." (PMID 32192494, 2020). "The results suggested that G. thunbergii extract could decrease Bcl-2 expression and increase Bax expression to regulate or induce gastric cancer cell apoptosis." (PMID 32158613, 2020). "In addition, myrrh inhibited the expression of PCNA, COX-2, and Bcl-2 as well as increased Bax expression in gastric cancer cells." (PMID 32364228, 2020).
gastric cancer (continued). "Western blotting showed that BBSKE treatment could also dose-dependently inhibit the expression of cycle-related proteins (bcl-2) in these gastric cancer cells." (PMID 32226516, 2020). "Besides, by directly interacting with the 3’UTR of Bcl2, miR-190b induces osteosarcoma cell apoptosis and confers radio-sensitivity to gastric cancer cells." (PMID 33344235, 2020). "Similarly, mulberry anthocyanins suppress the proliferation of SGC-7901 gastric cancer cells and upregulate their expression of caspase-8 and beclin-1, as well as increasing the Bax/Bcl-2 ratio." (PMID 32911639, 2020). "Tanshinone IIA induces apoptosis through mitochondrial- and caspase-dependent pathways, which includes caspase-3, -9 and PARP activation, cytochrome c release, and increased ratio of Bax/Bcl-2 in human gastric cancer MKN45 and SGC-7901 cells, and tumor-bearing mice." (PMID 31719837, 2019). "We further examined the expression of miR-1915-3p and Bcl-2 in gastric cancer tissues and found that miR-1915-3p was negatively correlated with Bcl-2 expression in gastric cancer tissues in which the lower expression level of Bcl-2 corresponds to higher level of miR-1915-3p." (PMID 31036603, 2019). "Therefore, the present study aims to explore the expression of miR-1915-3p and its target gene, Bcl-2, in gastric cancer." (PMID 31036603, 2019). "However, there is lack of investigation about the relationship between miR-1915-3p and Bcl-2 in the development of gastric cancer." (PMID 31036603, 2019). "Exogenous upregulation of miR-15/16 was shown to reverse the multidrug resistance of a gastric cancer cell line to a panel of anticancer drugs via direct regulation of the anti-apoptotic BCL2 protein and to induce the intrinsic apoptosis pathway via negative regulation of BCL2 expression in CLL." (PMID 35582270, 2019). "Hence, miR-1915-3p possibly contributes to the development and progression of gastric cancer by inhibiting the anti-apoptotic protein Bcl-2." (PMID 31036603, 2019). "Moreover, METTL3 knockdown decreased Bcl2 and increased Bax and active Caspase-3 in gastric cancer cells, which suggested the apoptotic pathway was activated." (PMID 30886897, 2019). "Raddeanin A is a pentacyclic triterpenoid saponin, isolated from A. raddeana, and induces apoptosis in multiple cell lines by means of increased Bax expression, reduced Bcl-2 and Survivin expression and the activation of caspases 3, 8 and 9 in gastric cancer cells." (PMID 30862032, 2019). "Consistently, Zey treatment markedly decreased the levels of pro-caspase-3, indicating that Zey treatment induced gastric cancer cell apoptosis via caspase-3 activation and the involvement of anti-apoptotic proteins Bcl-xl and Bcl-2 and pro-apoptotic protein Bax." (PMID 30150551, 2018). "Increased Bcl-2 expression has been identified as a reason for resistance to 5-fluorouracil in other GI tumors, too, but the posttranscriptional regulation of mRNA coding for Bcl-2 is under the control of different miRNAs; e.g., in gastric cancer diminished expression of miR-204 is the reason." (PMID 29967761, 2018). "To confirm whether DSGOST can interfere with the interaction between Beclin-1 and Bcl-2, we examined the co-immunoprecipitation of Beclin-1 and Bcl-2 in DSGOST-mediated gastric cancer cells." (PMID 29844404, 2018). "A study on gastric cancer indicated that Bcl-2, a protein affecting apoptosis, might be the target of miR-204." (PMID 29382303, 2018). "TXNL1 has been reported to induce apoptosis by downregulating Bcl-2 in gastric cancer cells." (PMID 30290847, 2018). "while MGr1-Ag/37LRP might also influence the multi-drug-resistance of gastric cancer cells probably by regulating the expression of P-glycoprotein, Bcl-2 and Bax." (PMID 29069734, 2017). "In addition, M2-exos protected gastric cancer cells from chemotherapy induced apoptosis through the regulation of anti-apoptosis protein Bcl-2." (PMID 28407783, 2017).